CTLA4 (cytotoxic T-lymphocyte associated protein 4)
Diseases named in the same sentence as CTLA4 in open-access papers (continued):
Sharing a sentence is not in itself a finding about the gene and the disease.
tumor (continued). "As NeoAg vaccines have demonstrated favorable safety profiles, combining NeoAg vaccines with single agent ICT may yield robust anti-tumor immunity with less toxicity than anti-CTLA-4 and anti-PD-1 combination ICT69–72." (PMID 38187708, 2024). "Interestingly, combining NDV with anti-CTLA-4 antibody also showed synergistic effects in mouse tumor models by increasing CD8+ T cell infiltration while inhibiting tumor growth and prolonging survival time." (PMID 39055561, 2024). "ICIs, which target inhibitory immune pathways such as the PD-1/PD-L1 and CTLA-4 pathways, may reactivate exhausted T cells and restore immune surveillance against tumor cells, making them a promising therapeutic avenue in this context." (PMID 39682299, 2024). "Tspan9 expression was significantly negatively correlated with tumor immune-cell infiltration and the immune checkpoint CTLA4, Tspan9 can decrease tumor immune-cell infiltration, enrich immune-related signaling pathways, and express immune checkpoint proteins to exert its tumor suppressor effects." (PMID 38649381, 2024). "Tumor-infiltrating CD8+ T cells in HBV-associated HCC were highly activated but dysfunctional, showing impaired cytotoxicity and exhaustion, with significantly increased expression of immune checkpoint molecules, such as PD-1, CTLA-4, LAG-3, and TIGIT." (PMID 38793588, 2024). "The additional benefit observed with anti-CTLA-4 in subcutaneous tumours may reflect depletion of T regulatory cells (Tregs) or attenuation of CTLA-4-mediated inhibition of positive co-stimulation of effector T cells by CD2835." (PMID 39322643, 2024). "CTLA-4/B7 function in different phases in comparison to the PD-1/PD-L1 axis, and thus synergistic inhibition of both signaling pathways offers a potential solution to reduce tumor resistance during ICI monotherapy." (PMID 38384472, 2024). "Herein, we propose a mechanism for the resistance of PDAC to anti-PD-1 and CTLA-4 immunotherapies and re-assess the rationale for pursuing Treg-targeted therapies in light of recent studies that profiled the immune landscape of patient-derived tumour samples." (PMID 38873607, 2024). "Furthermore, lactate has been shown to regulate Foxp3-dependent RNA splicing through the Cytotoxic T-lymphocyte-Associated Protein 4 (CTLA-4) pathway, maintaining the stable phenotype and function of tumor-infiltrating regulatory T cells (Tregs)." (PMID 39877360, 2024). "inhibition of CTLA-4 signaling similarly decreases regulatory T cell function and may contribute to a general increase in T cell responsiveness, including anti-tumor immune responses." (PMID 39136027, 2024). "Moreover, tumor-infiltrating and circulating T cells in e-cigarette exposed mice showed increased levels of immune checkpoints including CTLA4 and PD-1." (PMID 39221247, 2024). "Anti-CTLA-4 monoclonal antibodies can also deplete Tregs, and in cancer patients, there is a strong correlation between the clinical efficacy of Ipilimumab and the reduction of Treg numbers in tumor tissues." (PMID 39227959, 2024). "For in vivo studies, we utilized immunocompetent C3H/HeOuJ mice for subcutaneous tumor growth by injecting murine H&N cancer cell lines (SCCVII and MEER) and determined anti‐tumor activities of several combinations of immune checkpoint inhibitors, including anti‐CTLA‐4 antibody and APG‐157." (PMID 38686626, 2024). "Combination immunotherapy may be possible due to the simultaneous checkpoint blockade with antibodies to CTLA-4 and the anti-tumor effects of iNKT cell activation with conjugated BiTEs." (PMID 38243252, 2024). "CTLA-4 is one of the important targets for tumour immunotherapy." (PMID 39474352, 2024). "Thus, pharmacological targeting of the CTLA-4/B7 complex is believed to deliberate T-cell activity from cancer-mediated paralysis and serve as a potential tumor-agnostic target." (PMID 38920700, 2024).
tumor (continued). "These ICIs operate through distinct mechanisms: CTLA-4 inhibitors boost tumor-specific T-cell activation and proliferation by promoting CD28-mediated co-stimulation, while PD-1/PD-L1 inhibitors restore the function of tumor-infiltrating T cells by reversing negative signaling." (PMID 38541669, 2024). "This study hypothesized that blocking the “don’t eat me” anti-macrophage phagocytic signaling with anti-CD47 Ab and activating the “eat me” macrophage phagocytic signaling with anti-CTLA4 Ab could enhance anti-tumor efficacy." (PMID 38398223, 2024). "Combination blockade of CTLA-4 and PD-1 on their own are insufficient for controlling tumor growth." (PMID 39436696, 2024). "It was reported that PD-1 was significantly expressed in exhausted CD8 T cells, and in contrast to CTLA4 blocking, the effect of PD-1 blocking may be concentrated in remaining tumor T cells." (PMID 39256364, 2024). "Therefore, inhibition of CTLA-4 has been thought to directly activate T cells and release T cell-mediated immunosuppression by Tregs, resulting in long-term anti-tumor effects." (PMID 39106430, 2024). "Detailed search strategy was as follows: (PD-1 OR PD-L1 OR CTLA-4 OR ICIs OR immune checkpoint inhibitor) AND (lung OR pulmonary) AND (tumor OR cancer OR carcinoma OR neoplasm) AND (prognostic nutritional index OR PNI) AND (survival OR prognosis OR prognostic)." (PMID 38384634, 2024). "Combining these 2 results, we can speculate that CTLA-4 can upregulate T cells in PNI+OSCC tumours and thus have an immunotherapeutic effect." (PMID 39474352, 2024). "Despite this limitation, the authors demonstrated that the administration of anti-CD40 improves the efficacy of anti-PD-1 and anti-CTLA-4 in terms of primary tumour and metastasis formation in CRC without MMR deficiency." (PMID 39271762, 2024). "However, the parallel expression of regulatory T cells and the co-inhibitory molecule CTLA-4 between TILs and splenocytes hint at potential immune modulation within the tumor." (PMID 38672617, 2024). "The current perception of CTLA-4 biology focuses almost entirely on the membrane-bound receptor, and it is the activity of this isoform that almost all studies focus on to elicit greater anti-tumor immune responses." (PMID 38053333, 2024). "Three cases of PTC showed co-expression for PD-L1 and CTLA-4 in tumour cells." (PMID 39286684, 2024). "Ctla4 KO alone showed similar ability in tumor control to CUL5 KO." (PMID 38242867, 2024). "However, recent studies have identified novel properties of anti-CTLA-4 treatment in activating anti-tumour immune responses, such as Fcγ receptor engagement-mediated myeloid activation." (PMID 39322643, 2024). "They discovered that mice with GBT and overexpression of the vascular endothelial growth factor C (VEGF-C) demonstrate a better response to anti-tumor therapy, such as the combination of anti-programmed death-1 protein (PD1) and cytotoxic T-lymphocyte-associated protein 4 (CTLA-4) blockade." (PMID 38317779, 2024). "Our research using an MC38 mouse subcutaneous tumor model indicated that the synergistic use of TF and anti‐CTLA‐4 led to a pronounced increase in CD8+ T‐cell infiltration and a suppression of tumor growth compared with the effects of TF, anti‐PD‐1, or anti‐CTLA‐4 alone." (PMID 38938284, 2024). "Additionally, the tumor tissue was ground and filtered into a single-cell suspension, and the CTLA4 protein level was detected using Western blot." (PMID 38398223, 2024). "This study postulates that concurrently targeting CD47 and CTLA4 could intensify the anti-tumor effects by simultaneously blocking the “don’t eat me” signal while triggering the “eat me” signal." (PMID 38398223, 2024). "In addition, the expression or blockade of CTLA-4 on circulating T cells also impacts tumor defense." (PMID 38515578, 2024). "Anti-CTLA4 Ab has demonstrated promising anti-tumor effects across various cancer types." (PMID 38398223, 2024).
tumor (continued). "Notably, the combination of MRTX849, anti–PD-1, and anti–CTLA-4 induced tumor control by enhanced immunity in this otherwise strongly immune-evasive model." (PMID 39485838, 2024). "Interestingly, anti-TGFβ monoclonal antibodies (mAbs) played a synergistic role in further enhancing the anti-tumor effect of anti-CTLA4 mAb." (PMID 38891044, 2024). "Moreover, the combination of anti-PD-1 and anti-CTLA-4 with whole tumor cell vaccination exhibited impressive results and was able to counter the adaptive immune resistance to elicit strong tumor efficacy in a mouse NBL model." (PMID 39199637, 2024). "Consequently, CTLA-4 dampens T-cell responses by interacting with a network of immune and tumor cells, producing an immunosuppressive environment." (PMID 38956700, 2024). "Blocking CTLA-4, such as with inhibitors like Ipilimumab, can reverse the inhibitory effect on T cells, reactivating their immune response against tumors and producing an anti-tumor effect." (PMID 39184916, 2024). "Also, in murine lung cancer models, LDRT further enhanced the effectiveness of CPIs such as anti-PD1 and CTLA-4, as confirmed by diminished tumor growth rates and prolonged survival." (PMID 39044839, 2024). "Therefore, the CTLA-4/B7-mediated immune checkpoint in tumor microenvironment (TME) is another important component of the tumor immune escape." (PMID 39635535, 2024). "Present immunotherapy approaches for the destruction of tumor cells include cancer vaccines, immune checkpoint blockades such as PD-1/PD-L1 inhibitors, CTLA-4 inhibitors, induction of cytotoxic T-lymphocytes, adoptive cell transfer-based therapy, and modulation of the TME to increase CTL activity." (PMID 36678877, 2023). "We examined PD1 and CTLA4 given their current role in immunotherapy as well as the epithelial to mesenchymal transition (EMT) signature, a critical stroma-associated driver of tumour progression in solid tumours." (PMID 36701029, 2023). "Monoclonal antibodies against immune checkpoint blockade molecules—such as CTLA-4 (cytotoxic T lymphocyte antigen 4), PD-1 (programmed cell death 1), and PD-L1 (programmed cell death ligand 1)—target the tumor microenvironment (TME) with an obvious objective response rate for KIRC." (PMID 36759775, 2023). "Additionally, cytoplasmic staining of CTLA-4 protein has been described in diverse tumor entities, suggesting a similar mechanism of CTLA-4 endocytosis in tumor cells as observed in T cells." (PMID 37415208, 2023). "These inhibitors, including anti-cytotoxic T-lymphocyte-associated antigen 4 (CTLA-4), anti-programmed cell death receptor-1 (PD-1), or its ligand (PD-L1) induced T cell activation mechanisms to mediate anti-tumor response, and thus has been used for the treatment in multiple cancers." (PMID 37620924, 2023). "Therefore, CSCs targeted therapies combined with FDA-approved PD-1/PD-L1 checkpoint inhibitors or dual CTLA-4 blockade provided significant anti-tumor effects and CSC eradication." (PMID 36810098, 2023). "Furthermore, in HCC tissues, CTLA-4 contributes to tumor growth by promoting immunosuppression through the induction of Treg activity and the production of indoleamine-2,3-dioxygenase and IL-10 in DCs." (PMID 36769116, 2023). "Indeed, in studies involving microneedle delivery of anti-CTLA-4 in an orthotopic mouse model of head and neck cancer, Gutkind and coworkers showed anti-tumor responses at doses significantly lower than that needed using systemic administration." (PMID 37007996, 2023). "The administration of antibiotics had a considerable negative impact on the efficacy of anti-PD-1 monoclonal antibody therapy, either alone or in combination with anti-CTLA-4 antibodies, resulting in increased tumor size, reduced antitumor effects and decreased survival in germ-free mice." (PMID 37298653, 2023). "Similarly, the blood and tumor tissues of patients with bladder cancer treated with anti-CTLA-4 antibodies showed a higher expression of ICOS CD4+ T cells." (PMID 38328405, 2023).
tumor (continued). "Immune checkpoints like PD1/PD-L1 and CTLA-4 are essential for tumor immunity escape." (PMID 37861728, 2023). "Immune checkpoint blockade (ICB) therapies, that is, using monoclonal antibodies to reinvigorate tumor-reactive, antigen-specific T cells from the inhibitory effects of CTLA-4, PD-1 and PD-L1 immune checkpoints, have revolutionized the therapeutic landscape of modern oncology." (PMID 37881432, 2023). "Indeed, inhibition of EZH2 improves the response to anti-CTLA4 by regulating tumor cytotoxic effector T cells and changing the phenotype of Tregs into effector-like T cells." (PMID 37928272, 2023). "Upregulation of PD-1/PD-L1/CTLA-4 leads to tumor immunosuppression in NSCLC." (PMID 36895477, 2023). "Therefore, we applied more indirect anti-tumor effects of CTLA-4-based ICI, reflected in w3 in the lymphocyte dynamic equations." (PMID 37174706, 2023). "VEGFC overexpression in tumors induces a stronger immune response followed by the application of anti-PD-1 or anti-CTLA-4 treatment, in which the tumors displayed decreased tumor volumes and tumor weight and showed longer survival compared to the Vector group in the mice." (PMID 37790751, 2023). "Thus, on the day of the lymph node sampling, the volume of the tumor node in the anti-CTLA-4-therapy group varied from 45 to 470 mm3, whereas in the control group the variations were less pronounced — from 110 to 380 mm3." (PMID 38435479, 2023). "Mechanistically, CTLA-4, PD-1, and PD-L1 inhibitors enhance T-cell proliferation and activation against malignant antigens; the T-cells are reinvigorated to recognize cancer cells, impeding tumor evasion from the immune system." (PMID 37168978, 2023). "Other immunological markers, such as CTLA-4 (an immunomodulatory mediator that downregulates T-cell activation, leading to the suppression of the anti-tumor BCG response), were also evaluated, and decreased levels of serum CTLA-4 were associated with a good response to treatment." (PMID 38067259, 2023). "One of the first identified inhibitory checkpoints—CD152, also known as T lymphocyte-associated protein (CTLA-4)—has been shown to prevent expansion of CD4+ helper T cells, boost regulatory T cells, and promote a pro-tumour immuno-suppressive phenotype." (PMID 37345033, 2023). "Furthermore, in addition to anti-PD-1 antibodies, the combination of nanoparticle-based PTT with anti-PD-L1 antibodies and anti-CTLA-4 antibodies also showed significant anti-tumor effects." (PMID 37869003, 2023). "CTLA4-activated-like tumors manifested a conditional immune state resembling a cancer cell-exploited escape phenotype, and there existed meaningful interaction between tumor CLTA4-induced portraits and immune-infiltrating cells." (PMID 37838657, 2023). "Interestingly, while CTLA-4 is a relevant target to enhance effector responses during cancer in some tumor models, blockade of CTLA-4 results in enhanced costimulatory signals and hyperproliferation of Treg cells which drove increased immune tolerance." (PMID 36960049, 2023). "They reported the anti-tumor effect studies of 30 MBq 177Lu-LLP2A treatment, alone and combined with immune checkpoint inhibitors (200 μg anti-PD-1, anti-PD-L1, and anti-CTLA-4 antibodies on days 9, 12, and 15 after tumor cell injection), in B16F10 tumor-bearing mice." (PMID 36632233, 2023). "Due to its molecular and histological characteristics, such as lower immunogenicity, low TMB, fewer tumor-infiltrating lymphocytes, fewer dendritic cells, and lower levels of PD-1+ and CTLA4+ cells, the efficacy of ICI therapy has been limited, although promising data were also reported in R/M ACC." (PMID 38138214, 2023). "Meanwhile, tumor-bearing mice also showed good safety and tolerability to continuous administration of plant-produced anti-CTLA-4 antibody since no apparent body weight loss (>10%) were observed throughout the experiment." (PMID 37711295, 2023). "CTLA-4 also represses the immune responses and promotes the survival of tumor cells." (PMID 36721212, 2023).
tumor (continued). "Mice administered with CTLA-4 antibodies rejected pre-established or injected tumours." (PMID 39086690, 2023). "Some studies have found that ipilimumab can induce Fc-mediated antibody-dependent cytotoxicity (ADCC)-mediated Treg cell reduction in Pancreatic cancer due to the infiltration of FcγR-dense myeloid cells in the tumor, which increases the sensitivity to CTLA-4 mAbs." (PMID 37936703, 2023). "In addition to T-cells, CTLA-4 is constitutively expressed on solid human tumour cells such as certain carcinomas, and a wide range of cancers express variable levels of CTLA-4." (PMID 36980582, 2023). "We further extended this work to include an assessment of the impact of age on response to immune checkpoint blockade and here results were even more striking, with aged mice showing a greatly reduced anti-tumor effect of treatment with the combination of anti-PD-L1 and anti-CTLA-4 antibodies." (PMID 37920465, 2023). "Immunohistochemical staining for CD4+ and CD8+ T cells showed remarkably increased numbers of CD4+ and CD8+T cells infiltrating into the tumor tissues in mice treated with the combination of B. longum 420 and anti-PD-1 and anti-CTLA-4 antibodies compared to the other treatment groups." (PMID 37340017, 2023). "Expression of PD-1 and CTLA-4 on tumor cells enables them to escape immune surveillance to some extent, while ICIs treatment enhances antitumor immunity and thus may treat cancer." (PMID 37297017, 2023). "Indeed, recent studies have shown that combination of anti-4-1BB and anti-CTLA4 have a cumulative effect on T-cell activation, tumor rejection, and patient survival." (PMID 38044986, 2023). "Furthermore, Cyp11b1‐deficient tumours had reduced expression of the immunoregulatory molecules CD274 (PD‐L1), CD152 (CTLA‐4) and IL‐10." (PMID 36861295, 2023). "We found that the use of a CTLA-4 blocker was found to be more likely to be beneficial for PC patients in Mcluster B. Therefore, the study of microbiome in the tumour microenvironment of PC can help provide new strategies for the selection of immunotherapy for patients with PC." (PMID 37745080, 2023). "It was found that the tumor burden can either be reduced or completely eradicated on day 18 post-implementation for the combined therapy if either the level of oncolytic virus or the rate of blockade of CTLA-4 is increased." (PMID 36766849, 2023). "In addition to this, other works have highlighted the use of interleukin-6 (IL-6) and cytotoxic T-lymphocyte-associated antigen 4 (CTLA-4) levels and tumour burden to predict the occurrence of irAEs." (PMID 37324003, 2023). "To further investigate the underlying causes and mechanisms of this excellent response to combined anti-CTLA-4 and anti-PD-L1 blockade after progression under single agent PD-1 inhibiting therapy, we performed a molecular pathological analysis of the tumor tissue." (PMID 37569431, 2023). "Similarly, the interaction between PD‐1 receptor and its ligand PD‐L1 and PD‐L2, that are expressed by both TILs and tumor cells such as CTLA‐4, can reduce proliferation, and survival of T‐cells." (PMID 37537787, 2023). "In addition, among the tumor-infiltrating lymphocytes (TILs), TREM1 deficiency led to significant attenuation in exhausted CD8+ T (T Exh) cells (CD8+Tim-3+CTLA-4+) while increasing the proportion of cytotoxic CD8+ T (T Cyt) cells (CD8+GzmB+CD25+)." (PMID 37651197, 2023). "Immune checkpoint inhibitors (ICIs) are monoclonal antibodies that act by blocking checkpoint proteins on the surface of immune cells (such as cytotoxic T-lymphocyte antigen-4, CTLA-4, or programmed death-1, PD-1) from binding with their partner proteins on the tumor cells." (PMID 37958363, 2023). "Tumor cells may also evade immune recognition by the overexpression of immune checkpoints such as cytotoxic T-lymphocyte antigen-4 (CTLA-4) and programmed cell death protein 1 (PD-1)." (PMID 37681880, 2023).